CRABP2 (cellular retinoic acid binding protein 2)
Diseases named in the same sentence as CRABP2 in open-access papers (continued):
Sharing a sentence is not in itself a finding about the gene and the disease.
cancer (47 papers, 2011 to 2025). A tumor composed of atypical neoplastic, often pleomorphic cells that invade other tissues. "In other types of cancer, CRABP2 is shown to be strongly associated with hippo pathway and integrin/FAK pathway." (PMID 38807101, 2024). "Increased Crabp2 levels have been found in various types of cancer, and are associated with poor patients’ survival." (PMID 30696915, 2019). "Similarly, CRABP2 has been linked to the modulation of retinoic acid signaling, affecting cell differentiation and apoptosis in cancer cells." (PMID 41301068, 2025). "Additionally, CRABP2 expression was elevated in cancer-associated fibroblasts (CAFs) at the single-cell level." (PMID 38186580, 2023). "Resistance to retinoids has been observed in certain PDAC cell lines, as well as other types of cancer, and may be associated with a deficiency in the cellular retinoic acid-binding protein 2 (CRABP2), which is involved in the intracellular transport of retinoic acid." (PMID 37130839, 2023). "To identify appropriate LUAD cell lines for siRNA-CRABP2 construction, we retrieved CRABP2 expression data for common human LUAD cell lines from the Cancer Cell Line Encyclopedia (CCLE) database hosted by the ATCC cell line bank." (PMID 39991584, 2025). "Emerging evidence suggests a correlation between the dysregulation of CRABP2 expression and the development of various human cancers." (PMID 39991584, 2025). "Accordingly, recent studies have reported abnormal expression patterns of CRABP2 in multiple tumors, with expression levels strongly correlating with cancer prognosis." (PMID 40305785, 2025). "Earlier research has highlighted the role of CRABP2 in the regulation of lipid metabolism 25, which is vital for cancer cell proliferation, invasion, and metastasis." (PMID 40657374, 2025). "Critical hub genes, including KRT16, KRT17, CST1, and CRABP2 emerged as central nodes with high connectivity across multiple cancer-related pathways in both datasets." (PMID 40725485, 2025). "In conclusion, plasma CRABP2 can be used as a diagnostic and prognostic marker for NSCLC to reduce cancer cell proliferation, migration, and invasion by targeting inhibition." (PMID 38915108, 2024). "In the two gene clusters, some genes associated with tumorigenesis and cancer progression, such as AGR2, MMP7, LXN, PIGR, and CRABP2, were identified." (PMID 36712886, 2022). "For the cancer specimens, CRABP2 high expression was observed in 75.6% (130/172) and the difference was statistically significant." (PMID 34632074, 2021). "Several novel genes including Sostdc1, S100a4, Crabp2, and Id3 were identified among the top upregulated genes in the cancer stem-like cell population." (PMID 34785704, 2021). "Cluster 0 and 6 were enriched in cells expressing genes related to cell cycle and cancer-associated proliferation (SFRP2, CENPF, TOP2A, UBE2C, CRABP2, MYC)." (PMID 33771987, 2021). "Cluster 7 included cells with aberrant neuronal identity that expressed neuronal development genes (NEFM, DCX, STMN2, HES6) but also cell cycle and cancer-related genes (CRABP2, CCND1, MYC)." (PMID 33771987, 2021). "The expression of known cancer-related genes such as Sostdc1, S100a4, Crabp2, and Id3 was significantly upregulated in the cancer stem-like cell cluster." (PMID 34785704, 2021). "We then addressed the potential implication of Crabp2 knockdown in inhibiting the growth of cancer cells as compared with that by gemcitabine or irinotecan alone." (PMID 30696915, 2019). "While increased CRABP2 expression has been observed in AB1 embryonic stem cells with homozygous deletion of CRABP1, this is the first report demonstrating that CRABP1 has an inhibitory effect on CRABP2 expression in cancer cells." (PMID 26142905, 2015). "Given the established role of lipid metabolism in cancer progression, we concluded that CRABP2 may regulate the lipid metabolic pathways of NSCLC cells to support growth and metastasis." (PMID 40657374, 2025).
cancer (continued). "Most of cancer patients with high CRABP2 expression may benefit from immune checkpoint inhibitor therapy." (PMID 39991584, 2025). "We further explored the function of CRABP2 in tumorigenic characteristics of NSCLC cancer cells." (PMID 40657374, 2025). "Importantly, suppression of CRABP2 or FNDC4 reduced cancer invasion, even in the presence of GRPR overexpression, suggesting that these genes play a critical role in LUAD metastasis." (PMID 39768218, 2024). "In addition, these studies revealed that eIF5A, BRD9, XRCC1, CYP1A1, and CRABP2 were miR-486-3p-regulated cancer-promoting genes in NSCLC cells." (PMID 37508549, 2023). "For the cancer cell subtypes, we found that compared with Clara-like cancer cells (Epi-C1) and CRABP2 + cancer cells (Epi-C3), the proportions of both TM4SF1 + (Epi-C0) and UBE2C + (Epi-C6) cancer cells were constantly increased during the invasive process of LUAD and dramatically elevated in IAC." (PMID 36434043, 2022). "Moreover, mechanism study suggested that CRABP2 was a downstream effector of dezocine, which is involved in the anti-cancer activity of dezocine." (PMID 36568517, 2022). "We further explored the correlation of CRABP2 with cancer cell stress in human lung tumors." (PMID 30696915, 2019). "Reduction of CRABP2 level will suppress the movement of cancer cells." (PMID 31419991, 2019). "However, CRABP2 expression in pan-cancer showed an opposite pattern." (PMID 41301068, 2025). "Some researchers have discovered that the hot spot mutations of TERTp could trigger the aberrant expression of several cancer-related genes, such as cellular retinoic acid binding protein 2 (CRABP2), murine double minute 4 (MDM4), and myotubularin related protein 3 (MTMR3)." (PMID 39934880, 2025). "Transcriptomics and proteomics as a whole identified key DEPs of the THRB(−/−)/RL95-2 cells, including cellular junctions, metabolism, and cancer-related pathways, suggesting RARβ, CRABP2, and RXRA could be potential targets for MPA resistance and targeted by CANA." (PMID 40371351, 2025). "Overexpression of CRABP2 in EC109 cells resulted in decreased proliferation and increased apoptosis and decreased cancer cell migration." (PMID 41149452, 2025). "Previous studies have demonstrated that overexpression of CRABP2 and FNDC4 can enhance cell invasion and metastasis in various cancers." (PMID 39768218, 2024). "Given the roles of CRABP2 and FNDC4 in cancer progression, they are being explored as potential biomarkers or therapeutic targets in various cancers." (PMID 39768218, 2024). "The cancer cell subtypes enriched in the cancer region were CRABP2 + cancer cells (Epi-C3), and NK cells (T/NK-C5: NKG7) and mast cells (Mye-C0: TPSB2, Mye-C9: CPA3) were also located in the cancer region." (PMID 36434043, 2022). "Within community 2, we also identified increased expression of regulators of cell proliferation (CENPE, MKI67, TOP2A, UBE2C, guanine), cancer, and pluripotency (DNMT3B, DPPA4, MYC, POU5F1, CRABP2)." (PMID 33771987, 2021). "CRABP1, CRABP2, CYP and RAR expressions can be upregulated or downregulated depending on the cancer type and administrated anticancer drugs." (PMID 30322383, 2018). "In our EST database we see an overexpression of cellular retinoic acid binding protein 2 (CRABP2) together with MYCN proteins that have been shown to be upregulated and correlated in variety of cancers." (PMID 25243088, 2014). "A hepatisis-related study has indicated that CRABP2 can promote lipid droplet accumulation 25, yet its effect on lipid metabolism in cancer cells have not been thoroughly characterized." (PMID 40657374, 2025). "CRABP2 can also affect EMT process and chemoresistance to cancer cells." (PMID 38807101, 2024). "It is, therefore, proposed that the ratio of CRABP2 and FABP5 and the status of expression of their corresponding nuclear receptors may determine RA sensitivities of cancer cells." (PMID 29596381, 2018).
cancer (continued). "Interestingly, SGS organoids showed collectively more proliferating progenitors, which expressed markers of cancer-related proliferative genes (e.g., CRABP2, EGFR) virtually absent, or low in controls." (PMID 34193871, 2021).
infection (3 papers, 2018 to 2024). The state of being infected such as from the introduction of a foreign agent such as serum, vaccine, antigenic substance or organism. "Compared with the blank group, the expression level of CRABP1 in mice induced by H9N2 infection decreased at 3 and 5 days, while the expression level of CRABP2 increased at the same time." (PMID 35764970, 2022).
adenocarcinoma (2 papers, 2021 to 2023). A common cancer characterized by the presence of malignant glandular cells. "Using IHC, the protein expressions of CRABP2, DHCR24, and AK4 were examined using 44 adenocarcinomas including AIS (n = 7), MIA (n = 21), and SIA (n = 16)." (PMID 37004157, 2023).
CRABP2 also shares sentences with these, for which no sentence is quoted: pancreatic adenocarcinoma (2 papers); stomach adenocarcinoma (2); testicular germ cell tumor (2); atherosclerosis (1); atopic dermatitis (1); benign papillomas (1); bladder cancer (1); breast invasive carcinoma (1); cardiovascular diseases (1); cervical squamous cell carcinoma (1); Chiari malformation type II (1); colon tumors (1); COVID-19 (1); cyst (1); degenerative joint disease (1); diffuse large B-cell lymphoma (1); dyslipidemia (1); endocervical adenocarcinoma (1); esophageal adenocarcinoma (1); head and neck tumors (1); hepatoblastoma (1); kidney chromophobe (1); lamellar ichthyosis (1); leiomyoma (1); lipoblastoma (1); malignant peripheral nerve sheath tumor (1); mesothelioma (1); metastasis (1); nerve sheath tumor (1); oral squamous cell carcinoma (1).
A further 11 diseases each share a sentence with CRABP2 in 1 paper.